IL4 (interleukin 4)
Diseases named in the same sentence as IL4 in open-access papers (continued):
Sharing a sentence is not in itself a finding about the gene and the disease.
Sepsis (continued). "In this research, the surgical control group had IL-4 levels higher than those with sepsis, but no references were found that could explain this fact." (PMID 29257842, 2017). "By contrast, sepsis CD1a−negative DC induced less IL-4 and TGF-β in MLR cultures." (PMID 23071758, 2012). "The study aims to explore whether glutamine essentially supports M2 polarization in IL-4-stimulated murine macrophages by sustaining the activity of PDH and whether glutamine augments macrophage M2 polarization and thus alleviates inflammation and organ injury in a murine burn sepsis model." (PMID 36601059, 2022). "These associations between pre-sepsis immune dysfunction and mortality are supported by studies showing that sepsis impairs production of IL-1, IL-6, TNF-α, IL-12, and IFN-γ and suggesting that this sepsis-induced immunosuppressive state may be augmented by release of IL-4 and IL-10." (PMID 35271683, 2022). "In addition, the administration of miR-223 over-expressed macrophages with IL-4 pre-conditioning, but not IL-4 stimulated control cells, attenuated sepsis severity in LPS injected mice as evaluated by serum creatinine, liver enzymes, lung histology and serum cytokines." (PMID 32658933, 2020). "Furthermore, CD43-/-septic mice exhibited a prominent Th2 skewing following sepsis relative to WT septic mice, as evidenced by a significant decrease in the frequency of IL-2+ CXCR3+ TH1 cells as a significant increase in the frequency of IL-4+ CCR4+ TH2 cells." (PMID 30226896, 2018). "To clarify whether AAM were involved in the L. sigmodontis-mediated protection against an E. coli-induced sepsis, we used IL-4Rα/IL-5 double deficient BALB/c mice—which do not develop AAM, and IL-4-deficient BALB/c mice, which lack the suppressive effect of AAM." (PMID 25611587, 2015). "The data from clinical studies of sepsis showed that the plasma concentrations of IL-1β, IL-6, IL-8, MCP-1, IL-10, and IL-4 were significantly higher in non-survivors when compared with survivors." (PMID 32153410, 2020). "Sepsis did not markedly alter IFN-γ and IL-4 production by iNKT cells without α-Galcer treatment." (PMID 39720538, 2024). "IL-4+ ILC2, however, did not significantly increase following sepsis." (PMID 29511181, 2018). "Moreover, serum levels of IL-1β, IL-2, IL-4, IL-10, IL-17, IFN-α, IFN-β and IFN-γ were not elevated in severe sepsis survivors compared with sham-operated control mice (data not shown)." (PMID 23808943, 2013).
depression (152 papers, 2006 to 2026). "Conversely, in males, inflammation was inversely associated with depression severity, with protective effects from regulatory mediators (IL-2, IL-4, IL-6, IL-15, LIF, TNF-α, β-NGF) against depression." (PMID 40305313, 2025). "It is also associated with diseases such as depression and hypertension, and can influence the secretion of the host’s anti-inflammatory cytokine IL-4." (PMID 41514732, 2025). "The results suggested that both the lower level of IL-4 and age of onset were risk factors for depression in TA patients (OR [95% CI] 0.124 [0.018, 0.827], p = 0.031; 0.870 [0.765, 0.990], p = 0.035, respectively)." (PMID 38426163, 2024). "Studies suggest that IL-4 is linked to greater resilience against stress-induced depression, promoting increased BDNF and affecting serotonin transporter activity, thereby enhancing serotonin availability in the synaptic cleft." (PMID 39335507, 2024). "Our study has reported the age of onset and IL-4 were risk factors for depressed TA patients and showed the depression group was more active in the disease for the first time." (PMID 38426163, 2024). "By investigating IL-4, we aim to understand the association between pro- and anti-inflammatory processes in depression associated with cancer." (PMID 39355088, 2024). "Clinicians need to be vigilant about the decline of IL-4 in order to predict the potential risk of depression in TA patients and respond positively." (PMID 38426163, 2024). "The lower level of IL-4 and age of onset were the independent risk factors for depression in TA patients (OR [95% CI] 0.124 [0.018, 0.827], p = 0.031; 0.870 [0.765, 0.990], p = 0.035, respectively)." (PMID 38426163, 2024). "Interleukin-4 (IL-4) upregulation has been linked to major depressive disorder and myeloid differentiation factor 88 is associated with neuroinflammation." (PMID 39680432, 2024). "Levels of regulatory cytokines like TGF and IL-4 were negatively associated with HADS depression score and with short duration of illness in CFS." (PMID 34589849, 2020). "IL-4 is known to be implicated in psychiatric disorders, in particular, in the pathogenesis of depression." (PMID 33193575, 2020). "IL-10, another key anti-inflammatory cytokine, suppresses the production of pro-inflammatory mediators such as TNF-α and IL-1β, while enhancing tissue regeneration and immune homeostasis.In depression-related studies, elevated IL-4 levels have been associated with better emotional stability." (PMID 40453075, 2025). "Our result that the lower level of IL-13 was associated with depression might be related to the synergy of IL-4 reduction, with the need for further research to prove it." (PMID 38426163, 2024). "Meta-analysis showed that IL-4 was higher in the test group than in the control group (SMD: 1.01, 95% CI: 0.35, 1.67), indicating that depression animals treated with acupuncture had significantly higher levels of IL-4 (P < 0.05)." (PMID 41244868, 2025). "In recent years, the roles of pro-inflammatory cytokines (e.g., TNF-α, IL-1β) and anti-inflammatory cytokines (e.g., IL-4, IL-10) in the pathophysiology of depression have been increasingly clarified." (PMID 40453075, 2025). "Our findings indicate that acupuncture can reduce TNF-α and IL-1β levels while increasing IL-10 and IL-4 levels in depression animals." (PMID 41244868, 2025). "Patients with anxiety and depressive disorders have increased levels of pro-inflammatory cytokines (e.g., TNFα, IL-1α, IL-1β, IL-4, IL-5, IL-6, IL-12, and interferon [IFN]-γ) and C-reactive." (PMID 39803412, 2025). "IL-4, a type of Th2 cytokines with anti-inflammatory effects, has been widely reported to have a protective effect on depression in pre-clinical studies." (PMID 38627683, 2024). "Conversely, interleukins like interleukin-10 (IL-10) and interleukin-4 (IL-4) have distinct but interconnected roles in immune system regulation and its relationship with depression." (PMID 39335507, 2024).
depression (continued). "At 1 month after enrollment, the severity of depression was related to IL-1β (B 0.75, P = 0.04), IL-2 (B 1.41, P = 0.01) and IL-4 (B 0.91, P = 0.01)." (PMID 38459460, 2024). "This study presented that the serum levels of IL-4 were significantly decreased in TA patients with depression." (PMID 38426163, 2024). "NF-κB inhibition was one of the main downstream effects of TREK-1 blockage, IL-4 administration, NLRC5 deficiency, and CTRP3 overexpression, and it was associated with reduced depression-like behaviors in UCMS mice." (PMID 38791125, 2024). "Brains of AD cases with comorbid depression, compared with AD alone, had increased IL-4 in the superior frontal gyrus and increased TNFα & IL-12p70 in the insula." (PMID 39526037, 2024). "Studies have shown elevated IL-4 levels in patients with severe depression while, others have demonstrated reduced IL-4 levels in acute depression." (PMID 39355088, 2024). "Animal models of depression have confirmed that high concentrations of pro-inflammatory cytokines and low concentrations of anti-inflammatory mediators like IL-10 and IL-4 in the brain correlate with the progression of depression." (PMID 39130643, 2024). "Specifically IL-4 was increased in the AD + depression group in the superior frontal gyrus and that IL-12p70 and TNFα were increased in the anterior insula." (PMID 39526037, 2024). "In studies of adult depression, more evidence has also been informed of elevated levels of IL-4 in peripheral blood." (PMID 38627683, 2024). "Some studies reported elevated levels of IL-4 in the peripheral blood of adolescents with depression compared to healthy adolescents." (PMID 38627683, 2024). "In our study, the authors found the levels of IL-4, IL-13, eotaxin, and IP-10 were significantly lower in the depression of TA patients." (PMID 38426163, 2024). "The results of the study showed that SNPs of eNOS, HSP70, FKBP5, miR-146a, ACE2, MAS1, SGK1, IL-4–589, IL-6–174, TNF-α–308, CRP–717, 5-HTTLPR, and BDNF genes are associated with the comorbidity of coronary heart disease and depression." (PMID 38745947, 2024). "The IL-4 effects on microglia also show benefit in depression where infusion of IL-4 alleviated IL-1β induced depressive behaviours in rats." (PMID 39526037, 2024). "The modulation of IL-4 in various brain regions and its impact on depression-like behaviors should be further explored." (PMID 38791125, 2024). "For example, studies included in a meta-analysis found an association between increased levels of IL-1RA, IL-6, IL-10, IL-12, sIL-2R, sIL-6R, and TNF-α, and decreased levels of IFN-γ and IL-4, in adult patients with depression." (PMID 38474387, 2024). "It is generally accepted that IL-4 exerts anti-inflammatory effects through the suppression of the proinflammatory milieu; however, there are inconsistent reports on changes in IL-4 in depression, and the data are limited compared to other cytokines." (PMID 38791125, 2024). "The RvD1, NLRP3, IL-1β, IL-18, and IL-4 serum levels were dynamically evaluated before and after 6-8-week anti-depression treatment." (PMID 38627683, 2024). "The authors found that depression was correlated with lower levels of IL-4, IL-13, eotaxin, and IP-10, suggesting the abnormal immune responses contributing to the evolution of depression in TA." (PMID 38426163, 2024). "In the present study, we investigated association between levels of IL-4, BDNF, neopterin and depression in lymphoma patients receiving consecutive cycles of chemotherapy." (PMID 39355088, 2024). "Although not significantly altered, IL-6 levels tend to be upregulated (p = 0.0691) and IL-4 downregulated (p = 0.0746) in depression patients." (PMID 37575572, 2023). "In bipolar depression, IL-6 seems to be the predominant cytokine, IL-4 dominates in the euthymic state, and IL-2, IL-4, and IL-6 are prevalent in the manic state, while patients with unipolar depression mainly have elevated TNF-α, IL-6, and sIL-2R." (PMID 37510730, 2023).
depression (continued). "Compared with healthy controls, the levels of interleukin-4, interleukin-6, and interleukin-10 changed significantly in major depressive disorder patients." (PMID 37275977, 2023). "Conversely, enhancing IL-4 signaling to increase Arg-1+ microglia restored hippocampal neurogenesis and resistance to stress-induced depression." (PMID 37881439, 2023). "Supporting this, increased levels of proinflammatory cytokines including IL-1β and IL-6 and decreased levels of anti-inflammatory cytokines including IL-4 and IL-10 have been detected in people living with depression." (PMID 38053532, 2023). "IL-4 was 40% higher (MD: 1.40; 95% CI 1.14–1.72; p = 0.001) among patients with depression as compared to healthy controls, and still significantly higher after correction for multiple testing (p = 0.025)." (PMID 37016363, 2023). "Regarding anti-inflammatory cytokines IL-4 and IL-10 were unchanged between depression patients and controls." (PMID 37575572, 2023). "IL-1, TNFα, IFNγ, NGF, or microglia activation in depression, as well as IL-4, TNFα, and IL-10 in mania, were normalized by celecoxib in preclinical studies." (PMID 37240605, 2023). "A recent study found that the alternatively activated microglial phenotype (M2), which is activated by IL-4, enhances neurogenesis and thus ameliorates depression-like behaviors." (PMID 37881439, 2023). "Consistently, a previous study reported a trend of enhanced Th1 responses, as shown by an IFN-γ/IL-4 ratio, which was more obvious in female patients with depression." (PMID 36703721, 2022). "At baseline, TNF-α (F = 36.699, p < 0.001), IFN-γ (F = 8.907, p < 0.001), IL-4 (F = 66.256, p < 0.001), and IL-2 (F = 9.162, p < 0.001) levels in the depression group were significantly different from those of healthy controls." (PMID 35722555, 2022). "The level of IFN-γ, IL-4, and IL-2 were significantly higher in HC group than that of the depression group." (PMID 35722555, 2022). "The levels of neuropeptide Y (NPY), testosterone (T), and IL-1β, IL-6, TNF-α, IL-10, and IL-4 in the peripheral blood plasma of normal people, patients with depression, and patients with DCMI were measured." (PMID 35432561, 2022). "All study groups in which PTSD coexisted with depression showed lower IL-4 concentration levels than those with PTSD alone." (PMID 35326343, 2022). "The immune effects of IL-1β, IL-4, IL-10 and IL-8 in depression or PTSD have also been reported by other authors." (PMID 35326343, 2022). "The results showed that the levels of NPY, T, IL-10, and IL-4 in the normal group, depression group, and DCMI group were from high to low." (PMID 35432561, 2022). "Recently, the role of anti-inflammatory cytokines in attenuating the effect of inflammatory mediators (i.e., IL-10, IL-4, and IL-1ra) has also been taken into account in depression studies." (PMID 35886944, 2022). "Lastly, our study was unable to evaluate some immune markers and cytokines previously linked to WNV infection such as IL-2, IL-4, IFN-B, TLR-3, IL-11, and IL-18, as well as some previously linked to depression such as IL-18 and NFκB." (PMID 35745504, 2022). "In BD depression, IL-6 is the predominant cytokine, in euthymic state it is IL-4, and in manic episode it is IL-2, IL-4, IL-6, while patients with unipolar depression have mainly elevated TNF-α, IL-6 and soluble IL-2 receptor (sIL-2R)." (PMID 36294388, 2022). "The study assessed the concentration of IL-1β, IL-4, IL-8 and IL-10 in depression alone and with PTSD." (PMID 35326343, 2022). "There was an improvement in depression levels and a decrease in IL-4 and IL-5 in the IS and in the EBC in both groups." (PMID 34521963, 2021). "One strength of our study is that even the CG presented more cough-free days and better IL-4, IL-5, and depression levels after the protocol." (PMID 34521963, 2021).
depression (continued). "It is well established that patients with depression and anxiety have higher plasma levels of C-reactive protein and proinflammatory cytokines (e.g., TNFa, IL-1a, IL-1b, IL-4, IL-5, IL-6, IL-12, and interferon)." (PMID 33802143, 2021). "In this study, this benefit was evidenced by a reduction in airway inflammatory markers, such as IL-4, IL-5, IL-17A, FeNO and lung function, which consequently resulted in better quality of life and decreased depression levels." (PMID 34521963, 2021). "For the comparison of bipolar depression versus unipolar depression, an area under the curve (AUC) of 0.69 with 0.62 sensitivity and 0.66 specificity using three selected biomarkers (IL-4, thiobarbituric acid reactive substances, and IL-10) was achieved." (PMID 33578686, 2021). "•Patients with depression show increases in pro-inflammatory immune markers mean levels, and reductions in anti-inflammatory IL-4." (PMID 32113908, 2020). "Depression (TST) is associated with the presence of TNF-α, IL-12 and IL-4 in the cerebellum and with TNFα in the hypothalamus." (PMID 33322180, 2020). "Interleukin-4 (IL-4), one of the most important anti-inflammatory cytokines, was recently found to be downregulated in depression in a meta-analysis by Osimo." (PMID 33255237, 2020). "Multiple therapeutic targets were mediated by active ingredients of XYS, such as IL2, IL4, IL6, IL10, and STAT3, which are involved in immune and inflammatory responses closely associated with depression." (PMID 32256358, 2020). "IL-6 and IL-4 were the main contributing cytokines for prediction of the geriatric depression scale, and all the top cytokine variables also contributed to the prediction of the Schwab and England ADL scale." (PMID 31372494, 2019). "We confirmed that the M1 markers (IL-1β, IL-6, TNFα, iNOS, and CCL2) were induced and that the M2 molecules (Ym1, Arg1, IL-4, IL-10, and TGFβ) were impaired in depression." (PMID 27716270, 2016). "Meanwhile, some studies found that in patients with severe depressive disorder, the activation of proinflammatory cytokines and inhibition of interferon-gamma, interleukin-2, and interleukin-4 were documented." (PMID 27955661, 2016). "In a clinical study, patients with depressive episodes demonstrated an increase in IL-6 levels, whereas patients with maniac episodes showed an increase in IL-2, IL-4, and IL-6 levels." (PMID 23497121, 2013). "IL-4 demonstrated significant negative associations with PROMIS-Depression (rs= 0.35; 95% CI -0.61, -0.03; p = 0.034) and PROMIS-Anxiety scores (rs = -0.37; 95% CI -0.62, -0.05; p = 0.025), but associations with CES-D were not significant." (PMID 41938855, 2026). "In our review, we noticed that IL-4 decreased with the administration of the SSRIs escitalopram (one study, moderate depression) and sertraline (one study, unipolar depression), as well as with ketamine (one study, patients with treatment-resistant depression)." (PMID 40573262, 2025). "The inconsistency of cytokine alterations between anxiety and depression suggests that deficits of anti-inflammatory cytokines like IL4/IL-10 may be disease specific." (PMID 41462928, 2025). "on adults, indicating that serum IL-4 levels are elevated in adolescents with depression." (PMID 39980978, 2025). "Studies in AD and depression have shown discrepancies in IL-4 expression." (PMID 39526037, 2024). "Clinicians can probably use serum IL-4 level testing as a potential indicator of depression in TA." (PMID 38426163, 2024). "In our study, the significant increase of IL-4 in the peripheral blood of adolescents with depression and further increase after fluoxetine treatment may confirm the protective role of IL-4 in the pathophysiological process of adolescents with depression." (PMID 38627683, 2024). "This can explain that a decrease in IL-4 may indicate a lower proportion of Th2 cells, leading to an increase in the Th1/Th2 ratio, which can lead to TA patients with depression." (PMID 38426163, 2024).